U3 (Small nucleolar RNA U3 )
Synonyms: LOC124902596
Gene: Small nucleolar RNA gene on chromosome 10 (28,408,039 to 28,408,251, reverse strand). Ensembl gene ENSG00000222666.
Gene Ontology:
Biological process: RNA processing
Cellular component: nucleolus
Homologues: Orthologues: chimpanzee U3 (99% identical), macaque U3 (80% identical). Paralogues in human: U3 (75% identical), U3 (74% identical), SNORD3G (74% identical), U3 (73% identical), U3 (70% identical), SNORD3P1 (70% identical), SNORD3H (69% identical), U3 (69% identical), SNORD3E (68% identical), U3 (68% identical), U3 (67% identical), SNORD3D (67% identical), and 13 more.